HES1 (hes family bHLH transcription factor 1)
Diseases named in the same sentence as HES1 in open-access papers (continued):
Sharing a sentence is not in itself a finding about the gene and the disease.
tumor (continued). "Immune profiling revealed increased immunosuppressive tumor-associated macrophages (e.g., IL4I1, HES1) and monocyte-recruiting chemokines in non-responders." (PMID 40097400, 2025). "Using tumor samples collected from the Lgr5-specific Ythdf1cki mouse model, qPCR analysis revealed that YTHDF1 knock-in increased the expression of NOTCH1 downstream targets, including MAML1, MAML2, HES1, and HEY1." (PMID 41423446, 2025). "Furthermore, cytokine/growth factor networks involving Hes1 and JAK-STAT pathways collaboratively mediate tumor immune evasion within the microenvironment." (PMID 40755759, 2025). "Conditional knockout of Hes1 in mouse models markedly slows tumor growth and increases the infiltration and activation of cytotoxic T lymphocytes (CTLs) in the TME, suggesting that targeting Hes1 may be an effective immunotherapy strategy." (PMID 40755759, 2025). "While TKO tumor cells were primarily NE (ASCL1+), TKO-Nicd1 organoid tumor cells were non-NE and expressed markers of prostate epithelium (Krt5+, Krt8+, Hes1+)." (PMID 39024561, 2024). "Since neutrophils (CD11b+Gr1+), and myeloid-derived suppressor cells (MDSCs, CD11b+Gr1high) were not initially distinguished, we compared HES1 expression between these populations in both the tumor and spleen of TC-1 tumor bearing mice." (PMID 39702544, 2024). "Under DAPT treatment, KEAP1-silenced cells did not in fact show significant variation in NOTCH and HES-1 protein levels or changes in the viability of tumor cells." (PMID 38791966, 2024). "We found that immune cells from spleens of tumor-bearing mice showed substantially reduced Hes1 expression in neutrophils and macrophages, but not in B cells, T cells, or DCs." (PMID 39702544, 2024). "Because HES1 is absent in all myeloid lineage cells that infiltrate the tumor tissues, CD11b+ myeloid cells were further examined to explain the cause of reduced tumor volume observed in HES1-deficiency." (PMID 39702544, 2024). "We conclude that depletion of Hes1 improved the overall TME and shifted it to an anti-tumor state." (PMID 39702544, 2024). "Next, we investigated the anti-tumor efficacy of CD4+ and CD8+ T cells with Hes1-cKO." (PMID 39702544, 2024). "Because most of the KRAS mutant CRCs also have APC mutation, we included both in our study cohorts and classify these cases into HES1 (+) and HES1 (−) groups according to the presence or absence of tumor nuclear expression of HES1." (PMID 37749297, 2023). "Indeed, forced expression of miR-138–2 suppressed the tumor growth in vivo along with a significant down-regulation of NOTCH1, MAML1, APH1A and HES1." (PMID 36973704, 2023). "Compared to HES1 (−) tumors, expression levels of Ki67 (p = 0.0268), RB1 (p = 0.0271) and Cyclin D1 (p = 0.0487) were all significantly upregulated in the HES1 (+) tumor cells." (PMID 37749297, 2023). "NOTCH2 expression was strongly linked to HES1 expression, while other NOTCH gene levels were not, as indicated by RNA-sequencing analysis of desmoid tumor samples." (PMID 37728427, 2023). "Concomitant with the overexpression of AQP4, genes related to the immune system were also over-expressed, such as CD74, HES1, CALD1, and HEBP2, indicating AQP4 may relate to immune factors of tumor progression." (PMID 36599974, 2023). "This reciprocal correlation between RASSF1A and HES1 was evident in the vast majority of human cancers, implying that the reported RASSF1A–HES1 interplay may be conserved among different tumor types." (PMID 35954292, 2022). "Our results indicate that Crenigacestat significantly inhibited NOTCH1 and HES1, whereas tumor progression was not affected." (PMID 35457006, 2022). "In NSCLC, LBX2-AS1 functions as tumor promoter that positively regulates Notch signal markers, Notch1, p21 and Hes1, expressions." (PMID 36229883, 2022). "Similarly, the Notch target genes Hes1 and Hey1 were found overexpressed in a significant portion of HNSCC tumours, again suggesting hyperactivity of Notch signalling in these tumour tissues." (PMID 34944837, 2021).
tumor (continued). "Furthermore, the activation of NICD translation into the nucleus regulated the expression of target genes, such as HES1 and HEY1, which play a key role in tumor stemness, metastasis, and multi-drug resistance." (PMID 34001269, 2021). "Thus, in our present study, data demonstrated that HES1 is a novel regulatory gene in BCSC self-renewal, BCSC population, cancer cell proliferation, and tumor formation of TNBC." (PMID 33390847, 2021). "Furthermore, the rescue assays from our in vitro data on the maintenance of BCSC stemness of TNBC as well as our in vivo data on the tumor formation of BCSC of TNBC, indicated that HES1 is involved in stemness of BCSCs in TNBC through Slug." (PMID 33390847, 2021). "HES1, which is a downstream target of Notch pathway and one of the important markers of CRC stem cells, is known to contribute to tumour relapses in CRC patients after 5-FU based chemotherapy, but the role of HES1 in chemoresistant CRC has not yet been elucidated." (PMID 34733591, 2021). "Similarly to SAHA, VPA decreased Notch activity through downregulation of HES1 (HES family bHLH transcription factor) and upregulation of p21 and p63 tumor suppressors in HCC." (PMID 34068438, 2021). "Furthermore, FOXP3 suppression can inhibit tumor invasion and metastasis via downregulating the angiogenic factor VEGF, the epithelial-mesenchymal transition (EMT), and the Notch1/Hes1 pathway." (PMID 37305162, 2021). "To investigate whether and how HES1 influences BCSC stemness of TNBC in vivo, we examined tumor formation probability using mouse xenograft models." (PMID 33390847, 2021). "Since HES-1 expression is sometimes preserved in non-neoplastic stromal cells of the colorectal mucosa, mRNA expression assays would have measured both tumor and stromal HES-1 expression." (PMID 32974155, 2020). "HIF-1 in the tumor niche is related to poor prognosis because it enhances tumor spread and CSC self-renewal, promoting the stem phenotype by enhancing Notch-Hes1 or ALDH expression." (PMID 33059744, 2020). "The importance of the NOTCH1/HES1/DLL4/VEGFA/MMP13 axis in cholangiocarcinogenesis was confirmed in a collection of human iCCA tumor patients, paving the path for further investigations into the role of these genes in this tumor type." (PMID 32042099, 2020). "According to the RISH and IHC analyses, the tumor from the MDNP/dCas9–miR‐524‐treated mice exhibited remarkably higher miR‐524 expression level, which led to significant inhibition of the expression of Smad2, Hes1, and Tead1." (PMID 30643726, 2019). "The overall results suggest the hypothesis that the altered HES1 plays a regulating role in precancer, ISCC, and ADC by synergizing with HPV-16 as the aggressiveness of the tumor increases." (PMID 30615540, 2019). "In ileal NENs, the low or absent expression of NOTCH and HES1 has led to hypnotize a possible tumour suppressor role of the NOTCH canonical signalling cascade." (PMID 31443481, 2019). "Finally, we found that administrating SFN inhibited the formation of THBE xenograft tumors in NOD/SCID mice and reduced the levels of IL-6, ΔNp63α, NICD, Hes1, and lung CSC markers in THBE xenograft tumor tissues." (PMID 31367260, 2019). "The activation of doxycycline-inducible NOTCH1 and NOTCH3 in TT cells, through treatment with increased doses of doxycycline, has demonstrated a dose-dependent increase in NOTCH1, NOTCH3 and HES1 protein, a decrease in ASCL1 levels and ultimately a reduction in tumour growth in vitro and in vivo." (PMID 31443481, 2019). "After HES1-siRNA transfected into SACC LM cells, the cell proliferation and cell apoptosis were tested by suitable methods; animal model was established to detect the change of growth ability of tumor." (PMID 29665790, 2018).
tumor (continued). "HES1 overexpression increased the size of CD133+ cells and the capacity of tumor sphere formation." (PMID 29652830, 2018). "Significant difference of Notch1 and Hes1 were observed between tumor and non-tumor tissues (P<0.001)." (PMID 27705934, 2017). "In the present study, all of the 44 tumor specimens were found to have moderate to strong positive Notch1 and Hes1 staining, while 27 out of 44 matched paraneoplastic specimens were identified with only slight to moderate expression." (PMID 27705934, 2017). "To confirm whether the tumor decrease was directly correlated with CSC blockade, we compared the molecular expression of NOTCH1 and HES1 in 10 mg/kg or vehicle group xenograft mice using Western blot and immunohistochemistry." (PMID 27108536, 2016). "Of note, bortezomib reversed tumor-induced downregulation of Notch receptors, Notch1 and Notch2, as well as increased the levels of cleaved Notch intracellular domain (NICD) and downstream targets Hes1 and Hey1 in tumor-draining CD8+T-cells." (PMID 26431276, 2015). "Hes1 binds to the promoter of p27 Kip1and reduces p27Kip1 expression in a variety of tumor cells and non-pulmonary vascular smooth muscle cells leading to these cells proliferation." (PMID 26380809, 2015). "Activated Notch1 and HES1 were also overexpressed in the cytoplasm and nuclei of PDAC tumor cells." (PMID 25483102, 2015). "Hes1, a Notch pathway target gene, was also found to be upregulated in the HCC tumor tissues." (PMID 25668819, 2015). "Tumor tissues were then embedded in paraffin, stained with hematoxylin and eosin (H&E), and immunohistochemically stained with antibodies against FOXA1, AR, Notch1, Hes1, Ki67, or PCNA." (PMID 24512546, 2014). "Reverse transcriptase - quantitative PCR (RT-qPCR) was utilized to quantify HES1, HEY1, NOTCH1 and NOTCH2 gene expression in matched tumor and normal metaphyseal bone samples taken from dogs treated for appendicular OSA at the Colorado State University Veterinary Teaching Hospital." (PMID 23816051, 2013). "This suggests that Hes1 expression cannot entirely substitute for enhanced Notch signaling during tumor progression." (PMID 19688092, 2009). "Interestingly, while a strong negative correlation was showed between HES1 expression and tumor volume in mice that received the vehicle alone (p = 0.0093 and r=-0.7942), a positive correlation in the mice that received 2OHOA was revealed." (PMID 39400678, 2025). "These contrasting findings may be due to the presence of HES1 in the nuclei of both stromal cells and immune cells in cases where tumor cells are negative for HES1." (PMID 37749297, 2023). "In the PDTX model, administration of SR3029 obviously delayed tumor growth, concomitant with an increased protein level of AES and a decreased expression of Wnt target genes (Axin2, Fibronectin and LEF1), stemness marker genes (CD44 and LGR5) and Notch target genes (HES1 and HES2)." (PMID 33754069, 2021). "Notably, tumor #2 exhibited only low LGR5 intestinal stem cell marker expression, but consisted of substantial amounts of enterocytes and secretory progenitor cells as depicted by high HES1 and SPDEF1 as well as moderate KLF4 expression, respectively." (PMID 33628739, 2020). "However, the expression of HES1, a proved Notch signaling downstream target, is not modified in tumor compared to healthy tissues." (PMID 30380753, 2018). "We first established that NOTCH signaling was active in multicellular tumor spheroids of H1299 and H460 cells, where we show that NOTCH target genes HES1 and cMYC were expressed and their expression could be blocked with 1 μM BMS-906024 already 2-days post-treatment." (PMID 30464927, 2018). "Finally, there is a good correlation in tumor samples between STRAP and HES1 expression." (PMID 29652830, 2018).
tumor (continued). "The tumor inhibition rate was evaluated, followed by the quantification of messenger ribonucleic acid (mRNA) and protein expression of notch signaling components NOTCH-1, NOTCH-3, NOTCH-4, JAG-1, DLL-4, Hes-1, and Hey-1 using quantitative polymerase chain reaction (qPCR)." (PMID 26762567, 2016). "LTβR-accelerated tumour burden was further documented by increased levels of the transfected oncogenes NICD, with increased levels of AKT, activated pAKTThr308, pAKTSer473, NICD and Hes1 observed at day 40 by western blot with liver lysates derived from AKT/NICD/anti-LTβR treated mice." (PMID 26206664, 2016). "In addition, the activation of HES1 in NSCLC leaded to tumor cell growth and tumor progression." (PMID 25996086, 2015). "HES1 expression oscillations are both observed and necessary for cell cycle progression during neuronal development; aggressive OSA tumor cells may utilize HES1 oscillatory patterns to manipulate the cell cycle and optimize their ability to metastasize and/or resist chemotherapy." (PMID 23816051, 2013). "Taking into consideration that CD44 is a transcriptional target of Notch-1, apparently downstream of Hes1/Hey1, we concluded that β-elemene could attenuate tumor angiogenesis by targeting GCSCs at least in part through Notch-1 expression." (PMID 23710217, 2013). "However Hes-1 expression was neither correlated with tumor grade (p = 0.237), nor with clinical stage (p = 0.397)." (PMID 23409141, 2013). "Hence, targeting macrophage expression of HES1 may be a more precise approach to restoring T-cell activity and suppressing tumor growth without interfering with other essential cellular processes." (PMID 39702544, 2024). "Finally, to determine whether there might be a relationship between HES1, YAP1, and CDKN1C in human tumor tissue, we examined their expression at the transcript and protein level (when available) in human RMS tumor samples by querying published databases generated for the RMS research community." (PMID 36037042, 2022). "Experimental NOTCH pathway inhibition as well as HES1 knockdown reduced oncogenic capacities in vitro, suggesting that the NOTCH pathway triggers oncogenic rather than tumor suppressive processes in T2E+ PCa." (PMID 33669024, 2021). "The rapid depletion of the non-glial Hes1+ populations after vismodegib treatment would also support a direct relationship between SMOM2-mediated SHH hyperactivation and Hes1 expression in tumor cells." (PMID 31863004, 2019). "Surprisingly, significant positive correlations between the expressions of POFUT1 and HES1 or HEY1 are found for healthy tissues and not for tumor ones." (PMID 30380753, 2018). "Although there was a significant inhibition of the pharmacodynamic marker HES1 post-treatment with MK0752, no noticeable change was observed in tumor morphology, tumor cell proliferation and induction of apoptosis between the control and treatment arms." (PMID 28473715, 2017). "Moreover, there were no marked differences in gene expression of key tumor cell division (p27, CDK4 and Hes1) and inflammation markers (F4/80 and IL-6) following metformin treatment." (PMID 34829914, 2021). "Multivariate Cox regression analysis showed that distant metastasis (P = 0.011) and tumor recurrence (P = 0.000) were independent prognostic factors for NPC patients, whereas Hes1 expression was not an independent prognostic factor for NPC patients (P = 0.053)." (PMID 26452025, 2015). "Having previously reported that Notch3 activation appeared to be associated with more aggressive disease, we have now examined components of this pathway (Notch1, Notch3, Notch4, HES-1, HEY-1) in more detail in resectable (n = 42) and non-resectable (n = 50) tumours compared to uninvolved pancreas." (PMID 23226563, 2012). "Therefore, HES1 may not be the best surrogate marker for the Notch signaling pathway, at least for AFX and PDS tumor cells." (PMID 40387567, 2025).
tumor (continued). "However, stem and progenitor cells in non-pathological intestinal regions, as well as in tumor cells, undergo differentiation into goblet cells following inhibition of NOTCH1/HES1 signaling, a non-specific targeting of these pathways could cause severe side effects." (PMID 37860822, 2023). "Thus, even HES1 and HEY1 do not always track together and need to be studied independently, and their expression and function may differ depending upon cell line and tumor microenvironment." (PMID 36037042, 2022). "Moreover, the high Lef1 levels in the tumor cells appeared not to be a result of the deregulated Notch signaling, as inhibition of the Tcf1−/− tumor cells by DAPT only mildly affects Lef1 levels, whilst both Notch target genes Hes1 and Deltex were completely down-regulated." (PMID 23185135, 2012).